MTSS1 (MTSS I-BAR domain containing 1)
Description:
May be related to cancer progression or tumor metastasis in a variety of organ sites, most likely through an interaction with the actin cytoskeleton.
Synonyms: KIAA0429; MIM; MIMA; MIMB
Tractability: Small molecule: a structure with a bound ligand is known. Antibody: the Human Protein Atlas places it where antibodies can reach. PROTAC: its protein half-life has been measured.
Gene: Protein-coding gene on chromosome 8 (124,550,776 to 124,728,775, reverse strand). Ensembl gene ENSG00000170873.
Subcellular location: Cytoplasm, cytoskeleton
Subcellular location (Human Protein Atlas): Cytosol; Plasma membrane
Gene Ontology:
Molecular function: actin monomer binding; identical protein binding; protein binding; signaling receptor binding; actin binding; phospholipid binding
Biological process: actin cytoskeleton organization; adherens junction maintenance; cell adhesion; cell surface receptor protein tyrosine kinase signaling pathway; cellular response to fluid shear stress; epithelial cell proliferation involved in renal tubule morphogenesis; glomerulus morphogenesis; microspike assembly; negative regulation of epithelial cell proliferation; nephron tubule epithelial cell differentiation; positive regulation of actin filament bundle assembly; renal tubule morphogenesis; plasma membrane organization
Cellular component: actin cytoskeleton; cytoplasm; endocytic vesicle; ruffle; cytoskeleton
Genetic constraint (gnomAD): Loss-of-function variants: 17 observed, 76.87 expected, observed/expected ratio (o/e) 0.22, 90% interval 0.15 to 0.33. The upper end of that interval is the gene's LOEUF score, 0.33, which puts it in group 1 of 6, group 1 being the genes least tolerant of losing a copy. Missense variants: 812 observed, 1,012.3 expected, observed/expected ratio (o/e) 0.8, 90% interval 0.76 to 0.85. Synonymous variants: 341 observed, 379.12 expected, observed/expected ratio (o/e) 0.9, 90% interval 0.82 to 0.98.
Homologues: Orthologues: chimpanzee MTSS1 (99% identical), macaque MTSS1 (99% identical), dog MTSS1 (97% identical), pig MTSS1 (97% identical), mouse Mtss1 (97% identical), rabbit MTSS1 (96% identical), rat Mtss1 (96% identical), guinea pig MTSS1 (95% identical), tropical clawed frog mtss1 (81% identical), Drosophila melanogaster mim (36% identical), Caenorhabditis elegans M04F3.5 (21% identical). Paralogues in human: MTSS2 (57% identical).
Diseases named in the same sentence as MTSS1 in open-access papers:
MTSS1 is named in the same sentence as 90 diseases in open-access papers, as found by Europe PMC text mining. Sharing a sentence is not in itself a finding about the gene and the disease. The quoted sentences say what the papers report.
breast carcinoma (34 papers, 2008 to 2025). "Subsequent studies revealed that MTSS1 is associated with the inhibition of metastasis in a variety of cancers including hematopoietic and breast cancers." (PMID 39519115, 2024). "Loss of SCAMP1 and MTSS1 in breast cancer tissues associated with poor disease-specific survival in HER2+ breast cancer patients." (PMID 35992869, 2022). "MTSS1 downregulation causes early carcinogenesis and results in increased metastatic spread as well as poor survival rates in breast cancer and lung cancer." (PMID 31848385, 2019). "This was clinically tested in HER2 breast cancer tissue and shown that loss of MTSS1 and SCAMP1 correlates with reduced disease-specific survival." (PMID 29497041, 2018). "Specifically, findings from large cohort breast cancer clinical samples indicated that decreased MTSS1 expression was positively associated with poorer prognosis, whereas high levels of MTSS1 correlated with an increased overall patient survival." (PMID 24318128, 2013). "The presence of MTSS1, which encodes for metastasis suppressor 1 appears paradoxal, given its favorable prognostic impact in breast cancer." (PMID 21339811, 2011). "Notably, lower MTSS1 expression was associated with poorer prognosis in patients with breast cancer." (PMID 40066676, 2025). "In this study, we identified a novel function of SNHG15 to suppress the transcription of the MTSS1 gene in breast cancer cells." (PMID 39519115, 2024). "In breast cancer, MTSS1 interacts with the E3 ligase RBCK1, enhancing RBCK1-mediated ubiquitination and degradation of p65, thereby inhibiting the NF-κB signaling pathway that is essential for the self-renewal of TICs." (PMID 39625546, 2024). "MTSS1 expression is relatively low in breast cancer, glioblastoma, diffuse large B-cell lymphoma (DLBCL), and nasopharyngeal carcinoma compared with control tissue from healthy subjects." (PMID 39625546, 2024). "This is a mechanism of the MTSS1-mediated suppression of tumor-initiating cells (TICs, also called cancer stem-like cells) seen in breast cancer mouse models." (PMID 39625546, 2024). "For example, it was confirmed that MTSS1 expression is decreased in esophageal, ovarian, prostate, colorectal, and breast cancers, although hepatocellular carcinoma and breast cancer were found to have higher levels of MTSS1 expression." (PMID 37635248, 2023). "Inhibition of aerobic glycolysis then significantly reduces the role of MTSS1 in breast cancer cell migration and invasion as well as breast cancer metastasis." (PMID 36672448, 2023). "Cong, M used breast cancer organoids to explore the molecular mechanism of metastasis suppressor 1 (MTSS1)." (PMID 37537666, 2023). "Previous studies in our group have shown the critical roles of MTSS1 in the regulation of breast cancer progression." (PMID 36810288, 2023). "In this regard, EGF-induced miR-15b was shown to stimulate the migration of breast cancer cells, through the suppression of the MTSS1 gene." (PMID 35406622, 2022). "MTSS1 has been characterized as a tumor suppressor in breast cancer and chronic myeloid leukemia, however overexpression of MTSS1 has been observed in melanomas and hepatocellular carcinomas." (PMID 35768865, 2022). "In breast cancer cells, SCAMP1 prevented cell invasion via cooperation of MTSS1 (metastasis suppressor protein 1) in breast cancer." (PMID 35992869, 2022). "In summary, we provide evidence of the cooperative roles of MTSS1 and SCAMP1 in preventing HER2+/ER−/PR− breast cancer invasion and we show that the loss of Mtss1 and Scamp1 results in a more aggressive cancer cell phenotype." (PMID 29497041, 2018). "SCAMP1-regulated MTSS1 prevents a more aggressive cancer cell phenotype and its loss is responsible for reduced survival in patients with HER2+/ER−/PR− breast cancer." (PMID 29497041, 2018). "We showed that restoring Mtss1 expression in HER2+/ER−/PR− breast cancer cell lines promoted cell–cell adhesion and prevented cell invasion." (PMID 29497041, 2018).
breast carcinoma (continued). "To better understand the role of MTSS1 and SCAMP1 in tumour progression, we investigated their influence on cell migration and invasion using HER2+ breast cancer cell lines, and MTSS1-expressing and SCAMP1-expressing constructs." (PMID 29497041, 2018). "To begin this investigation, we first analyzed MTSS1 protein levels in various prostate and breast cancer cell lines." (PMID 24318128, 2013). "Consistent with our findings, high levels of MTSS1 expression was also found in breast cancer or hepatocellular carcinoma patients with a favorable prognosis in the previous reports." (PMID 21696600, 2011). "In prostate cancer and breast cancer, expression of MTSS1 has been shown to be reduced, whereas up-regulation of MTSS1 expression has also been observed in hepatocellular carcinoma." (PMID 21696600, 2011). "This notion is clearly supported by a recent study showing that biological overexpression of MTSS1 significantly suppressed the invasive, migratory, growth and adherence properties of a human breast cancer cell line." (PMID 20712855, 2010). "Moreover, tumor metastasis suppressor gene-1 (MTSS1) regulates aerobic glycolysis in breast cancer by affecting HK2 kinase activity, and inhibits aerobic glycolysis in breast cancer by competitively binding to mitochondria-targeted HK2." (PMID 36672448, 2023). "Previous studies have proved that MTSS1 could function as a tumor suppressor in a number of cancers including colorectal, ovarian and breast cancer." (PMID 36496997, 2022). "miR-96 has also been reported to be increased in breast cancer; its overexpression may suppress breast cancer cell migration by downregulating the expression of MTSS1." (PMID 35768865, 2022). "In line with the tumor-suppressive actions of MTSS1, we found an inverse correlation between high expression of miRNA-15b and low expression of MTSS1 in tissues from breast cancer patients with the aggressive basal subtype, whereas low abundance of MTSS1 correlated with poor patient prognosis." (PMID 34206026, 2021). "Furthermore, we determined the translational importance of this proposal in a clinical setting by showing that loss of MTSS1 and SCAMP1 expression are specifically associated with a worse prognosis in HER2+/ER−/PR− breast cancer." (PMID 29497041, 2018). "Indeed, we found that SCAMP1 expression correlated with Mtss1 expression in tumours with the HER2+/ER−/PR− phenotype and its expression was decreased similarly to MTSS1 in the HER2+/ER−/PR− breast cancer class." (PMID 29497041, 2018). "However, a new discovery in 2015 can verify that there is an inverse correlation between the high expression of miRNA-15b and the low expression of its target gene MTSS1 in the tissues of breast cancer patients with the aggressive basal subtype." (PMID 28340554, 2017). "Furthermore, an inverse correlation was also observed between MTSS1 expression and poor prognosis in breast cancer." (PMID 24318128, 2013). "Given that a significant decrease in MTSS1 abundance is frequently observed in both prostate and breast cancers, we sought to investigate whether MTSS1 expression in these cancer cells inversely correlates with cellular proliferation and migration." (PMID 24318128, 2013). "Notably, we found that the PC3 prostate cancer cells and the MDA-MB-231 breast cancer cells displayed a significantly reduced expression of MTSS1, whereas DU145 and MCF-7 cells expressed relatively high MTSS1 levels." (PMID 24318128, 2013). "Finally, four genes (PTPN2, MTSS1, EPN3, and C17ORF37) are associated with cell migration and adhesion and/or poor prognosis of breast cancer." (PMID 21339811, 2011). "Our study not only demonstrated that SNHG15-mediated MTSS1 suppression promotes breast cancer progression but also revealed a molecular mechanism by which an lncRNA like SNHG15 could serve as a regulator to repress gene transcription via interacting with the gene promoter." (PMID 39519115, 2024).
breast carcinoma (continued). "We showed that in breast cancer cells, lncRNA-SNHG15-induced cell invasion and proliferation was accompanied with the decreased expression of MTSS1 mRNA." (PMID 39519115, 2024). "MTSS1 ablation enhanced the mammary epithelial TIC subpopulation in both luminal and basal-like breast cancer mouse models." (PMID 39625546, 2024). "In breast cancer, RPL37A expression, in conjunction with metastases suppressor 1 (MTSS1), as well as SET and MYND domain-containing protein 2 (SMYD2), were shown to predict the response of breast cancer patients to neoadjuvant doxorubicin and cyclophosphamide." (PMID 36008952, 2022). "It has been reported that miR-15b is highly expressed in breast cancer and promotes its progression by binding to the 3′ untranslated region (UTR) of metastasis suppressor protein 1 (MTSS1) and downregulating its expression." (PMID 32175269, 2020). "Subgroup analysis was performed to test the relationship of MTSS1 expression with disease-specific survival and metastasis outcome in HER2+ breast cancer." (PMID 29497041, 2018). "This decrease of MTSS1 expression correlated with reduced survival and worse prognosis in HER2+/ER−/PR− breast cancer patients." (PMID 29497041, 2018). "To investigate the expression of endogenous MTSS1 and SCAMP1 in breast cancer cell lines, we performed immunoblotting (IB) using whole-cell extracts from SkBr3 and MDA-MB-453 (HER2+/ER−/PR−) and BT-474 (HER2+/ER+/PR+) human breast cancer cells." (PMID 29497041, 2018). "An increased cell migration of BT-474 breast cancer cells was also observed following combined MTSS1 and SCAMP1 knockdowns, and when compared to the control or when MTSS1 or SCAMP1 were individually knocked down." (PMID 29497041, 2018). "In this direction, we found a possible inverse relationship between MTSS1 and β-TRCP expression in both prostate and breast cancer cell lines." (PMID 24318128, 2013). "In women with breast cancer submitted to neoadjuvant chemotherapy based in doxorubicin, tumor expression of groups of three genes (PRSS11, MTSS1, CLPTM1 and PRSS11, MTSS1, SMYD2) have classified them as responsive or resistant." (PMID 18601734, 2008). "Moreover, the expression of metastasis‐suppressing genes, including MTSS1, TIMP2, Rb1, and PTEN, gradually increased with increasing Arid4a expression in human breast cancer samples." (PMID 40066676, 2025). "Since the MTSS1 gene plays a vital role in breast cancer metastasis, we hypothesized that SNHG15-induced breast carcinogenesis could be largely contributed to by the down-regulation of MTSS1 mRNA." (PMID 39519115, 2024). "In addition, we found that MTSS1 physically interacts with the E3 ligase RBCK1 to induce ubiquitination of the NF-κB subunit p65, leading to inhibition of breast cancer cell stemness." (PMID 36810288, 2023). "In addition to reducing RSU1, miR-182-5p promotes tumor cell proliferation, invasion and migration by targeting FOXF2, RECK and MTSS1, and the suppression of MTSS1 (MIM) by miR-182 activates RhoA and promotes breast cancer metastasis." (PMID 32751711, 2020). "Taken together, these results confirm our hypothesis of synergistic interaction between MTSS1-mediated and SCAMP1-mediated cellular pathways in preventing HER2+/ER−/PR− breast cancer invasion." (PMID 29497041, 2018). "Identification of MTSS1 and SCAMP1 as key regulators of HER2+ cancer progression by artificial neural network (ANN)-based integrative data mining HER2+ breast cancers are among the most aggressive type of breast cancer." (PMID 29497041, 2018). "To determine whether MTSS1 and SCAMP1 interact, we performed a proximity ligation assay (PLA) and immunoprecipitation (IP) experiment using whole-cell extracts from the BT-474 breast cancer cell line." (PMID 29497041, 2018). "Moreover, we reveal the dual role of MTSS1 and SCAMP1 in preventing HER2+ breast cancer progression." (PMID 29497041, 2018).
breast carcinoma (continued). "MTSS1 (also termed MIM for “missing in metastasis”) had initially been identified as a gene that was downregulated in cell lines from metastatic bladder, prostate, and breast cancer as compared to cell lines from patients with non-metastatic malignancies." (PMID 25996952, 2015). "MTSS1, a member of the IMD-family (IRSp53 and MIM (missing in metastasis) domain), serves as an actin-binding scaffold protein and stimulates the activation of Rac1-GTP, thus promoting cell–cell adhesions and preventing HER2+/ER−/PR− breast cancer cell migration and invasion." (PMID 35805075, 2022). "On the basis of this background, we hypothesised that the vesicle carrier protein SCAMP1 is involved in stabilising MTSS1 protein trafficking that promotes MTSS1 anti-invasive and anti-metastatic functions by endorsing cell–cell adhesion in HER2+ breast cancer." (PMID 29497041, 2018). "To investigate whether this hypothesis is translated in the clinical setting, we verified the presence and the expression of MTSS1, SCAMP1 and SERPIN B13 in a cohort of breast cancer patients by immunohistochemistry staining, using specific antibodies to these proteins." (PMID 29497041, 2018).
prostate carcinoma (19 papers, 2010 to 2024). A carcinoma that arises from epithelial cells of the prostate gland. "The underlying molecular basis of βTrCP in breast and prostate cancer is that βTrCP targets the MTSS1 (metastasis suppressor 1) protein and impedes its degradation by UPS, thus promoting tumorigenesis." (PMID 32882786, 2020). "Moreover, MTSS1 down-regulation was associated with elevated expression of miR-96 in prostate cancer." (PMID 39625546, 2024). "Interestingly, it was reported that all three MTSS1 splice variants were significantly reduced in prostate cancer, whereas overexpression of MTSS1 markedly reduced the proliferation of prostate cancer cells." (PMID 24318128, 2013). "Importantly, decreased MTSS1 expression is associated with more aggressive forms of breast and prostate cancers, and with poor survival rate." (PMID 24318128, 2013). "Decreased levels of MTSS1 mRNA due to promotor methylation were also reported for bladder urothelial carcinoma, prostate cancer, and chronic myeloid leukemia." (PMID 39625546, 2024). "Another study reported that three genes, FOXF2, RECK, and MTSS1, which act as tumor suppressors and are involved in inhibiting the development of prostate cancer cells by reducing invasion and migration, were targeted by miR-182-5p." (PMID 37438760, 2023). "Studies have shown that MTSS1 is notably downregulated during the progression of gastric cancer, and hypermethylated MTSS1 can promote the migration of prostate cancer." (PMID 36338652, 2022). "Recently, the functions of MTSS1 have been investigated in prostate cancer cell lines and have been shown to significantly reduce cell migration and proliferation." (PMID 30224667, 2018). "The prognostic value of MTSS1 downregulation has been demonstrated for solid tumors such as breast and prostate cancer." (PMID 25996952, 2015). "Studies examining prostate cancer have also revealed that the overexpression of MTSS1 clearly inhibits cell metastasis, growth and adherence." (PMID 25295101, 2014). "Recently the function of MTSS1 was examined in prostate cancer cell lines and found to significantly suppress cell migration and proliferation." (PMID 23383207, 2013). "Cell viability, invasion and migration were significantly inhibited in RECK and MTSS1 transfected prostate cancer cells." (PMID 23383207, 2013). "To examine the function of RECK and MTSS1, we overexpressed RECK and MTSS1 in prostate cancer cells which were confirmed by measuring mRNA and protein expression levels." (PMID 23383207, 2013). "Expression of MTSS1 has also been shown to be reduced in prostate cancer and can contribute to tumor growth and development, as well as metastasis." (PMID 20712855, 2010). "Since this pioneering article, other reports have indicated that MTSS1 played a role as a metastasis suppressor in prostate cancer, bladder cancer and benign lesions, but up-regulated in basal cell carcinomas." (PMID 20712855, 2010). "More importantly, both H3K27ac and RNA-seq data showed a much higher signal in the cancer cell line compared to the healthy cell line, indicating a possible effect of this PC-associated duplicated CNVR in enhancing the expression of NDUFB9 and MTSS1 genes in prostate cancer." (PMID 36768794, 2023). "Blocking MTSS1 degradation is thus a potential treatment for aggressive breast and prostate cancer." (PMID 33805973, 2021). "Therefore, in aggressive breast and prostate cancer, the prevention of MTSS1 degradation is considered as a potential treatment approach for these types of cancer." (PMID 32882786, 2020). "Additionally the levels of FOXF2, RECK and MTSS1 were significantly higher in xenograft tissues from low miR-182-5p expressing prostate cancer cells." (PMID 23383207, 2013). "It further suggests that preventing MTSS1 degradation could be a possible novel strategy for clinical treatment of more aggressive breast and prostate cancers." (PMID 24318128, 2013).